RNVU1-1 (RNA, variant U1 small nuclear 1)
Synonyms: vU1.1; U1P14; U1.4; vU1.10; RNU1-53; RNU1-10P; RNU1P10; RNVU1-10
Gene: Small nuclear RNA gene on chromosome 1 (148,362,370 to 148,362,533, reverse strand). Ensembl gene ENSG00000207340.
Gene Ontology:
Molecular function: pre-mRNA 5'-splice site binding
Biological process: mRNA 5'-splice site recognition
Cellular component: U1 snRNP
Homologues: Orthologues: chimpanzee U1 (96% identical), macaque U1 (96% identical), guinea pig U1 (95% identical), rat U1 (93% identical), rabbit U1 (90% identical). Paralogues in human: RNU1-1 (96% identical), RNU1-2 (96% identical), RNU1-27P (96% identical), RNU1-28P (96% identical), RNU1-3 (96% identical), RNU1-4 (96% identical), RNVU1-18 (96% identical), RNVU1-29 (96% identical), U1 (96% identical), RNVU1-28 (96% identical), RNVU1-7 (96% identical), RNVU1-31 (95% identical), and 133 more.